PARP1 (poly(ADP-ribose) polymerase 1)
Diseases named in the same sentence as PARP1 in open-access papers (continued):
Sharing a sentence is not in itself a finding about the gene and the disease.
ischemia (21 papers, 2009 to 2025). A hypoperfusion of the BLOOD through an organ or tissue caused by a PATHOLOGIC CONSTRICTION or obstruction of its BLOOD VESSELS, or an absence of BLOOD CIRCULATION. "We found that TRIM65 deficiency significantly increased PARP1 cleavage induced by intestinal ischemia-reperfusion injury." (PMID 38212319, 2024). "Our data show that photothrombotic focal ischemia was associated with an early PARP-1 activation occurring within the first 24 h with a maximal intensity observed at 4 h after the onset of ischemia which is consistent with previous reports." (PMID 19956568, 2009). "In our experimental conditions, PARP-1 inhibition by 3-AB treatment was associated with a very important decrease in OX-42 staining at 4 h (Fig. 4B1–2) and 24 h (Fig. 4D1–2) of ischemia as compared to vehicle treated animals." (PMID 19956568, 2009). "Over the past decade, PARP-1 inhibitors have been explored in a few clinical trials to treat ischemia." (PMID 38172953, 2024). "For example, it has been shown that DNA damage activates the enzyme poly (ADP-ribose) polymerase 1 (PARP1); and higher PARP1 activity and lower NAD+ level are associated with ischemia, neuroinflammation, and neurodegenerative diseases." (PMID 33804401, 2021). "PARP1-dependent poly(ADP-ribosyl)ation has been reported to be involved in cardiac ischemia/reperfusion injury, atherosclerotic plaque stability, fatty liver prevention and cell homeostasis." (PMID 30050067, 2018). "In order to investigate the role of microglial cells in the stimulation of neuroplastic changes, PARP-1 inhibition was used as a means of down-regulating the microglial response induced by ischemia." (PMID 19956568, 2009). "Therefore, miR-124 could negatively regulate PARP1 to alleviate renal ischemia-reperfusion injury by inhibiting TNFα/RIP1/RIP3 pathway, miR-124 may be exploited as a novel therapeutic agent to attenuate IRI in renal acute injury and kidney transplantation." (PMID 34131409, 2021). "Finally, a robust and important decrease of OX-42 and ED-1 staining was observed in 3-AB treated animals in the early phase of ischemia, confirming that PARP-1 inhibition is an efficient approach for the modulation of local resident microglial activation and proliferation." (PMID 19956568, 2009). "To confirm the role and mechanism of PARP1 in the development of MIRI, we established a MIRI animal model by 45 min of ischemia via ligating left anterior descending branch (LAD) of the SD rats, and then reperfused for 24 h." (PMID 34124031, 2021). "Researchers have shown that zinc is a key factor in transient global ischemia-induced microglial activation through sequential activation of NADPH oxidase and Poly (ADP-ribose) polymerase-1 (PARP-1)." (PMID 31818314, 2019). "They suggested that PARP-1 and calpain act in concert following calcium dysregulation to induce AIF release during ischemia." (PMID 22405498, 2012). "In our experimental conditions, photothrombotic ischemia leads to PARP-1 activation at 4 h and 24 h after the onset of ischemia as evidenced by a marked PAR immunostaining, the enzymatic product of PARP-1." (PMID 19956568, 2009). "Moreover, catalpol also suppressed PreOL death and differentiation arrest in an in vitro ischemia model through regulation of intracellular Ca2+ homeostasis and inhibition of mitochondrial damage, followed by attenuation of ERK1/2 and PARP-1 activation." (PMID 29966349, 2018). "Knockout of the TPRM2 protects male, but not female, mice from effects of ischemia, and interaction with the AR through PARP1 has been proposed as the mechanism." (PMID 26557979, 2015). "Consistent with a rapid PARP-1 activation described after focal ischemia, the PARP-1 inhibition was performed by 3-AB i.p. injection right after the induction of photothrombotic ischemia." (PMID 19956568, 2009).
ovarian tumors (20 papers, 2010 to 2025). "The PARP1 p.R591C mutation that inhibits PARP1 trapping ability was identified in a patient with ovarian tumor resistant to olaparib." (PMID 36284291, 2022). "The concept of synthetic lethality of repair enzymes has already been applied clinically with great success in the anticancer treatment of BRCA-deficient ovarian tumors treated with PARP1 inhibitors." (PMID 34300575, 2021). "The PARP1 inhibitor olaparib is approved for treatment of BRCA-mutated ovarian tumors." (PMID 26959114, 2016). "Consistent with PARP-1 activation in ovarian tumors, 68Ga-DOTA-Olaparib PET/CT imaging displayed high tumor accumulation in the SK-OV-3 model." (PMID 37145164, 2023). "PARP1 expression in ovarian tumor tissues was approximately 1.4 times of the normal ovarian tissues." (PMID 35875162, 2022). "We also evaluated PARP1 copy number status in TCGA PanCancer cohorts of primary breast and ovarian tumors." (PMID 36344544, 2022). "Further validation of key results (LOH transitions, PARP1 amplifications, BRCA2 isoform switching) in an independent cohort of paired primary and recurrent BRCA1/2 mutation-associated breast and ovarian tumors will be important." (PMID 36344544, 2022). "The systemic administration of semi-synthetic EV-mimetics loaded with CRISPR/Cas9 targeting poly(ADP-ribose)polymerase 1 (PARP-1) demonstrably reduced the PARP-1 expression significantly in ovarian tumor tissue, thereby reducing the tumor progression." (PMID 34203051, 2021). "Clinical validation of such approaches, commonly described as synthetic lethality (SL), has been provided by the regulatory approval of poly(ADP-ribose) polymerase 1 inhibitors (PARPi) as monotherapy for BRCA1/2-mutated breast and ovarian tumors." (PMID 31921645, 2019). "For example, PARP1, a PARP inhibitor, creates synthetic lethality in HR-deficient cancers, such as breast and ovarian tumors harboring BRCA1 and BRCA2 gene mutations." (PMID 28526069, 2017). "Confirming these findings, in a PARP inhibitor-resistant ovarian tumor, a mutated PARP1 was found that does not alter the mobilization of the PARP1 enzyme toward the damaged locus of DNA but prevents the trapping of PARP1." (PMID 35873570, 2022). "The functions of PARP10 appear to be distinct than those of PARP1, and its catalytic activity is not affected by PARP1 inhibitors, which have been recently approved for treatment of breast and ovarian tumors with BRCA mutations." (PMID 36187556, 2022). "We determined whether combined BRCA2 and PARP1 inhibition could prevent or delay growth of ovarian tumors in vivo." (PMID 26959114, 2016). "Similar results have been reported for other TSGs involved in controlling genomic stability, such as the inhibition of PARP-1 in BRCA1/2 deficient breast and ovarian tumors which selectively kills the cancer cells while sparing normal cells with a functional repair pathway." (PMID 21122106, 2010). "Notwithstanding the importance of PARP-1 in numerous pathways that govern genome integrity, the effective killing of HR-deficient BRCA1/2-mutated cancer cells by PARP inhibitors (PARPi) has been the basis for the development of therapies targeting breast and ovarian tumors." (PMID 37609662, 2023). "The antiproliferative activity against human ovarian tumor cells (A2780cis, OVCAR-3, and OAW-42) was evaluated by the MTT assay, focusing on the modulation of multidrug resistance (MDR) pumps and the PARP-1 enzyme." (PMID 40219097, 2025). "Rucaparib is a well-known inhibitor of PARP-1, PARP-2, and PARP-3 enzymes that is clinically used for the treatment of certain types of ovarian tumors." (PMID 36768904, 2023).
liver cancer (19 papers, 2008 to 2024). An epithelial or non-epithelial malignant neoplasm that arises from the liver. "Indeed, cccDNA levels directly correlate with the risk of developing liver cancer and tumor recurrence, in part by reducing the infected cell’s capacity for DNA repair through the sequestration of the DNA repair enzyme PARP-1." (PMID 37892121, 2023). "Here we identify unique aggressive liver cancer domains (ALCDs) that are activated in aggressive HBL by PARP1-mediated chromatin remodeling leading to elevation of modified TSPs and activation of additional cancer pathways: WNT signaling and β-catenin." (PMID 30271949, 2018). "The inhibition of PARP1 by specific drugs and siRNA inhibits formation of PARP1/Ku80/Ku70 complexes, silences multiple pathways of liver cancer, and results in inhibition of proliferation of cancer cells." (PMID 30271949, 2018). "It is important to note that a strong activator of aggressive liver cancer, β-catenin, is also under control of PARP1-ALCD axis and is dramatically elevated in examined aggressive HBL." (PMID 30271949, 2018). "The identification of a PARP1-dependent ALCDs in multiple pathways of liver cancer provides a strong rationale for the utilization of PARP1 inhibitors to treat aggressive liver cancer." (PMID 30271949, 2018). "Higher frequency (P < 0.001) of autoantibodies against PARP1 was found in breast, lung, ovarian, and liver cancers." (PMID 25865228, 2015). "The protein expression levels of CD95, caspase-8, caspase-3 and PARP1 in the tumor tissues and the corresponding normal tissues of 40 liver cancer samples were assessed by western blot analysis." (PMID 25543761, 2015). "In this study, our results showed autoantibody responses to PARP1 abundantly expressed in breast, lung, ovarian, and liver cancers." (PMID 25865228, 2015). "Almost all liver cancer cell lines have a higher PARP-1 protein expression than that observed in PHHs." (PMID 25139788, 2014). "The presence of PARP-1 at the protein level in liver cancer cells and detected poly(ADP-ribosyl)ation activity allowed us to investigate the effects of PARPi in these cell lines." (PMID 25139788, 2014). "Conversely, PARP1 may actively suppress some cancers, since PARP1 knockout mice show increased incidence of liver cancer with advancing age." (PMID 34830134, 2021). "These new findings include elevation of posttranslationally modified and inactive TSPs; discovery of ALCDs that drive aggressive liver cancer with PARP1 as the main activator; and evidence toward the use of PARP1 inhibitors to treat aggressive pediatric liver cancer." (PMID 30271949, 2018). "In liver cancer, autoantibodies frequency to three TAAs were 25.0% (19/76), 5.3% (4/76) and 0% (0/76), 5.3% (4/76), 0% (0/76) and 0% (0/76) were shown to have autoantibody to PARP1 and BRCA1, PARP1 and BRCA2, or BRCA1 and BRCA2, respectively." (PMID 25865228, 2015). "The results demonstrated that inhibition of the expression of PARP1 may improve outcomes in patients with liver cancer." (PMID 25543761, 2015). "However, the role of PARP1 linked with JAK-STAT signaling in drug resistant liver cancer has not been explored well." (PMID 34199353, 2021). "PARP1 is elevated in aggressive HBL form complexes with Ku80 and Ku70 and binds to the core 18 base pair sequence (18BPS) within a larger 250 bp aggressive liver cancer domain (ALCDs)." (PMID 30271949, 2018). "However, PARP-1 activity was reportedly reduced by 10 μM PJ34 in human colon and liver cancer cells." (PMID 26492236, 2015). "The present study demonstrated that the expression of PARP1 was higher in the liver cancer tissues compared with the normal liver tissues." (PMID 25543761, 2015). "However, it was not the fact in a study on liver cancer, which demonstrated that non-cancerous liver tissues had a higher PARP1 expression level than the liver cancer tissues." (PMID 33112558, 2020).
liver cancer (continued). "PARP-1 and PARP-2 mRNA expression appear to be up-regulated in most of the liver cancer cell lines studied in comparison with PHHs although not all the differences in expression were significant." (PMID 25139788, 2014).
COVID-19 (18 papers, 2020 to 2025). A disease caused by infection with severe acute respiratory syndrome coronavirus 2. "PARP1 was identified as an important marker of current or future severe COVID-19 and also was associated with risk of death." (PMID 33704068, 2021). "The link between ferritin and PARP1 further implicates DNA damage and repair pathways in the hyperinflammatory response of COVID-19." (PMID 41373577, 2025). "Published studies have shown that PARP-1 inhibition limits inflammation-induced tissue damage, including acute lung injury in animal models, and PARP-1 inhibitors have therefore been discussed as a potential treatment option for COVID-19." (PMID 37021417, 2023). "We also included olaparib, the first FDA-approved PARP1 inhibitor, in our further analyses, as this drug also achieved a high rank in our connectivity map analysis using the transcriptomic data of COVID-19 patients." (PMID 33895786, 2021). "The study of the role of miR-221-3p and the interaction with its target, PARP-1, during COVID-19 pathogenesis would be of great interest, since emerging evidence highlights relevant pro and antiviral properties of this protein." (PMID 35087533, 2021). "In this perspective, we summarize and discuss two important questions pertaining to the miRNA-mediated regulation of PARP-1 in the context of COVID-19 pathogenesis." (PMID 34698261, 2021). "First, how relevant is PARP-1’s activity across cell/tissue types in SARS-CoV-2 pathogenesis and second, can miRNA-mediated regulation of PARP-1 be exploited as a therapeutic target to prevent SARS-CoV-2 infection to mitigate COVID-19 pathological outcomes?" (PMID 34698261, 2021). "In this short perspective, we summarize the recent findings on the microRNA/PARP-1 axis and its therapeutic potential for COVID-19 pathologies." (PMID 34698261, 2021). "PARP1 inhibitors are in use for cancer, and our data suggest that re-purposing of PARP1 inhibition in COVID-19 should be explored further." (PMID 33704068, 2021). "For the treatment of COVID-19, a “poly-ADP-ribose polymerase 1 (PARP1)” now in Phase I trials, CVL218, may be an option." (PMID 35602132, 2022). "The regulation of PARP-1, particularly by miRNAs in the context of COVID-19 pathogenesis, may be of therapeutic relevance." (PMID 34698261, 2021). "It will be interesting and worth validating to identify if any of the PARP-1 regulatory miRNAs are altered in COVID-19 and whether there is any tissue/cell-type specificity in such alterations." (PMID 34698261, 2021). "Overall, our results indicated that the PARP1 inhibitor CVL218 identified by our integrative drug repositioning pipeline may serve as an effective therapeutic agent against COVID-19." (PMID 33895786, 2021). "Several of these diseases involving regulation of PARP-1 have been well documented as risk factors for COVID-19-associated mortality and hospitalizations, thus highlighting the plausible role of miRNA-regulated PARP-1 in COVID-19." (PMID 34698261, 2021). "Additionally, increasing evidence shows that the activation of PARP1 is the terminal point among a sequence of events culminating in patient mortality which should serve as the focus of COVID-19 immunotherapy." (PMID 34539756, 2021). "The immunity modulators, the aryl hydrocarbon receptor (AhR) and the nuclear NAD+-consuming enzyme poly (ADP-ribose) polymerase 1 (PARP 1) may play a critical role in COVID-19 pathophysiology." (PMID 33063092, 2020). "In regard to SARS-CoV-2 infection, it is interesting that PARP-1 inhibition has been shown to limit inflammation-induced tissue damage, including acute lung injury in animal models, and PARP-1 inhibitors are therefore discussed as a potential treatment option for COVID-19." (PMID 33233817, 2020). "For example, the inhibitor developed for the polymerase PARP-1 and HSPA9 can be used against COVID-19." (PMID 37047484, 2023).
COVID-19 (continued). "Using Venn diagram mapping, we further identified five core ferulic acid targets against OS and COVID-19 via autophagy, including MAPK1, TLR4, PIK3R1, STAT3, and PARP1." (PMID 36204096, 2022). "Recently, in silico screening followed by wet-lab validation indicated a poly-ADP-ribose polymerase 1 (PARP1) inhibitor, CVL218, currently in phase I clinical trial, for repositioning to treat COVID-19." (PMID 35336980, 2022). "Based on the data present in this study and the previously known evidences about the antiviral effects of PARP1 inhibitors reported in the literature, we propose several potential mechanisms to support the involvement of the CVL218 in the treatment of COVID-19." (PMID 33895786, 2021). "We showed that the PARP1 inhibitor CVL218 discovered by our integrative framework exhibits effective anti-SARS-CoV-2 activity in vitro and thus can be used as a potential drug candidate for treating COVID-19." (PMID 33895786, 2021). "Our in silico screening process followed by experimental validation revealed that a poly-ADP-ribose polymerase 1 (PARP1) inhibitor, CVL218, currently in Phase I clinical trial, may serve as a potential drug candidate to treat COVID-19." (PMID 33895786, 2021). "Based on the data present in this study and previous known antiviral effects of PARP1 inhibitors reported in the literature, we also discussed several putative mechanisms of the anti-SARS-CoV-2 activities for CVL218 to be involved in the treatment of COVID-19." (PMID 33895786, 2021). "Our in silico screening followed by wet-lab validation indicated that a poly-ADP-ribose polymerase 1 (PARP1) inhibitor, CVL218, currently in Phase I clinical trial, may be repurposed to treat COVID-19." (PMID 33895786, 2021).